BCL2L1 (BCL2 like 1)
Diseases named in the same sentence as BCL2L1 in open-access papers (continued):
Sharing a sentence is not in itself a finding about the gene and the disease.
melanoma (175 papers, 2004 to 2026). A malignant, usually aggressive tumor composed of atypical, neoplastic melanocytes. "In melanoma cells, overexpression of alternatively spliced Bcl-2-like protein 1 (BCL2L1, BCLXL) variants confers apoptotic resistance." (PMID 32346127, 2020). "For example, a common region of amplification at 1q21.2 included the histone methyltransferase SETDB1, which has been implicated in the onset of melanomas, and the apoptotic regulator BCL2L1 at 20q11 was also found recurrently amplified." (PMID 22685613, 2012). "BCL2-L1 was reported to be associated with melanoma resistance." (PMID 37174717, 2023). "Similarly, BCL2L1 is associated with melanoma cell survival, since its expression correlates with melanoma progression and treatment with antisense oligonucleotides resulted in reduction of cell viability." (PMID 20421967, 2010). "Alternatively, potentially targetable cancer types emerge (i.e., Ewing’s sarcoma and melanoma showing the highest ATP1A1/BCL2L1 levels)." (PMID 37904054, 2024). "Similar to what was observed in cell lines, miR-146a expression levels were inversely correlated with the levels of its target genes EGFR, CCL2 and BCL2L1 in melanoma metastases." (PMID 32967672, 2020). "While MCL1 expression in the CCLE data set was broadly similar in CRC and melanoma cells, and slightly higher in NSCLC and pancreatic, levels of BCL2L1 (encoding BCL-XL) were strikingly lower in melanoma relative to the other lineages." (PMID 31727888, 2019). "CDK4/6 inhibition in melanoma cells resulted in apoptosis associated with deregulation of BCL2, BCL2L1, BIRC5 and BIM." (PMID 30349650, 2018). "We have observed that a similar proportion of PAX3-positive cells were also BCL2L1-positive in melanocytes of normal skin, in naevi and in melanoma cells in all of the samples analysed." (PMID 20421967, 2010). "The exception is melanoma metastases, in which BCL2L1 was detected in only one sample (out of four) and both PAX3 and BCL2L1 were weakly stained and very rarely co-stain." (PMID 20421967, 2010). "A consistent lack of a significant decrease in the BCL-XL transcript level in melanoma cells exposed to 17-aminogeldanamycin might be explained by different NF-κB dimer compositions required for the activation of BCL2L1 expression." (PMID 32466509, 2020). "BCL2L1 expression in normal PAX3-positive melanocytes indicates that they might utilise the same cell survival regulatory mechanism as melanoma cells, in order to sustain continuous renewal in the ever-changing environment of the epidermis." (PMID 20421967, 2010). "It was also shown that following hypoxia exposure, melanoma cells bearing BRAF V600E mutation exhibit downregulation in the expression of genes encoding apoptotic regulators—BAD (Bcl-2-associated agonist of cell death) and BCL2L1 (Bcl-2-like 1, also known as Bcl-X)." (PMID 33918883, 2021). "In addition, among the genes indirectly regulated by miR-146a through NFkB activity, we found CCL2, IL6, and VEGFA, which contribute to the proinflammatory phenotype, CD274 (PDL1), which promotes melanoma cell proliferation, and BCL2L1 and MCL1 antiapoptotic genes." (PMID 32967672, 2020). "Overexpression of miR-596 in melanoma effectively inhibited the MAPK/Erk signaling pathway by downregulating MEK1, MCL1 and BCL2L1 levels." (PMID 40282319, 2025). "A positive correlation between BCL2L1 expression and phosphorylated STAT3 was also identified in melanoma models." (PMID 33803452, 2021). "Expression of both genes has been shown to increase in melanoma, while siRNA-mediated PAX3 downmodulation significantly decreased the expression of BCL2L1 in several melanoma cell lines." (PMID 32466509, 2020). "As the expression of BCL2L1 was markedly increased only in DMBC29 cells exposed to 17-aminogeldanamycin, these putative mechanisms might be, however, diversely involved in the regulation of BCL-XL level in different melanoma cell lines." (PMID 32466509, 2020).
melanoma (continued). "Finally, analysis of database of melanoma patients showed a significant correlation between the expression levels of HK2 and MCL1 (p = 2.3e-06, rho = 0.216) –but not BCL-2 (p = 1.98e-01, rho = 0.059) or BCL2L1 (p = 4.57e-01, rho = 0.034)." (PMID 41326406, 2025).
leukemia (140 papers, 1997 to 2026). A malignant (clonal) hematologic disorder, involving hematopoietic stem cells and characterized by the presence of primitive or atypical myeloid or lymphoid cells in the bone marrow and the blood. "We further investigated the correlation in specific tissue types/lineages, demonstrating that BCL2L1 remains one of the top-ranked genes whose expression is associated with Emax of E7107 in leukemia, lung, and ovarian cancer cell lines." (PMID 30635584, 2019). "Similarly, IL-6 or granulocyte-macrophage colony stimulating factor (GM-CSF) modulated alternative splicing of BCL2L1 in K562 leukemia cells towards its anti-apoptotic splice variant BCL-x(L)." (PMID 29286307, 2017). "This analysis revealed several genes that are specifically important for the growth of erythroid leukemia cells, including BCL2L1, which was recently shown to be essential for the survival of erythroid/megakaryocytic AML." (PMID 39277669, 2024). "SYC-522 treatment also decreased the expression of BCL2L1 in both MLL-rearranged leukemia cell lines." (PMID 24858818, 2014). "The increased expression of BCL2L1 induced by Wnt5a-activation of ROR1 may account in part for the enhanced resistance to venetoclax of leukemia cells that express high levels of ROR1." (PMID 35418613, 2022). "On the other hand, the involvement of AKT-Bcl-xL axis in venetoclax resistance in leukemia was reported before, and AKT pathway inhibition may facilitate the suppression of BCL2L1 in KG-1-FOXM1-KD cells." (PMID 34381718, 2021). "Collectively, these results indicate that expression of ROR1 was sufficient to enhance expression of NF-κB target genes, including BCL2L1, in MEC1 leukemia cells." (PMID 35418613, 2022). "The most prominent anti-apoptotic bcl-2 family members, including bcl-2 (B-cell CLL/lymphoma 2), bcl-XL (BCL2L1) and mcl-1 (myeloid cell leukemia 1; BCL2L3), were originally identified and found to be over-expressed in leukemia cells." (PMID 20105315, 2010). "The enKoRV in the exon region of BCL2L1, which is no longer present in the current captive population, showed a 21-fold higher chance of developing leukemia." (PMID 41513643, 2026). "It is important to note that both CCND1 and BCL2L1 gene expression also were decreased significantly in leukemia cell lines NB4 and HL-60, which do not have MLL rearrangement." (PMID 24858818, 2014). "In agreement with this hypothesis, several of the genes identified in our analysis have been suggested to be putative therapeutic targets in leukemia, with either preclinical or clinical trials underway (CDK4, CDK6, GSK3b, MYC, LCK, NFkB2, BCL2L1, NOTCH1)." (PMID 21356087, 2011).
lung carcinoma (137 papers, 2010 to 2025). "scRNA-seq of EGFR-mutated lung cancer patient samples also reveals high BCL2L1 expression, specifically in tumor cells, while MCL1 expression is lower in tumors compared to non-tumor cells." (PMID 39122703, 2024). "High expression of BCL2L1 elevated lung cancer patients death risk [hazard ratio (HR) and 95% confidence intervals (CI) = 1.60(1.38–1.86)], but no similar correlations were found in IGF1R, MAPK8, and FAS." (PMID 31508368, 2019). "One thousand nine hundred twenty-six patients with lung cancer were then recruited to study the association between differential expression of BCL2L1 and IGF1R and patient survival using Kaplan-Meier and Cox regression method." (PMID 30497474, 2018). "To validate the hypothesis, we adopted luciferase reporter plasmid assay by inducing mutation in the 3′-UTR region of BCL2L1, and the let-7a-5p mimics or inhibitors were co-transfected into the mutant or wild-type A549 lung cancer cells." (PMID 31508368, 2019). "Moreover, we assessed the death risk of lung cancer patients using 4 target genes related to let-7a-5p, including BCL2L1, IGF1R, MAPK8, and FAS." (PMID 31508368, 2019). "For instance, let-7a-5p downregulates the oncogene BCL2L1 by· thereby targeting it for gene silencing through association with a specific mRNA encoding protein activity that affects multiple signaling transcripts and inhibiting cell proliferation and migration/invasive phenotype in lung cancer." (PMID 41357196, 2025). "MDEs miR-let-7a-5p can be transferred to lung cancer cells, resulting in the inhibition of cell growth, migration, and invasion through the downregulation of Bcl2-like 1 (BCL2L1) expression." (PMID 41357196, 2025). "scRNA-seq of EGFR-mutated lung cancer cell lines captures changes in apoptosis-related gene expression following EGFR-TKI treatment, most notably BCL2L1 upregulation." (PMID 39122703, 2024). "BCL2L1 has made significant differences in tumor targeting therapy, as a novel tumor promoter, for hepatocellular carcinoma, lung cancer, gastric cancer, and cervical cancer." (PMID 34179092, 2021). "In a large chemical genomics study of more than 2000 compounds screened in over 100 human breast and lung cancer cell lines, low BCL2L1 expression was identified as the best predictor of sensitivity to transcriptional repressors." (PMID 32645016, 2020). "Previous studies confirmed that BCL2L1 negatively correlated with the survival of lung cancer patients." (PMID 32802131, 2020). "To investigate the role of let-7a-5p-BCL2L1 crosstalk in lung cancer, we performed functional annotation and signaling pathway enrichment for let-7a-5p." (PMID 31508368, 2019). "To explore the effect of let-7a-5p-BCL2L1 crosstalk on the migration of A459 lung cancer cells, we conducted wound healing assays." (PMID 31508368, 2019). "We found that overexpression of BCL2L1 led to autophagy suppression, but inadequate BCL2L1 promoted lung cancer cell migration and invasion." (PMID 31508368, 2019). "Knockdown of BCL2L1 suppressed the wound healing capability of A549 lung cancer cells, while overexpression of BCL2L1 enhanced the cells' wound healing capability." (PMID 31508368, 2019). "Based on the epidemiology survey and Kaplan-Meier survival analysis among 2,437 lung cancer patients, the alteration of BCL2L1 affects the lung cancer patients' survival." (PMID 31508368, 2019). "To reveal the role of let-7a-5p-BCL2L1 crosstalk on autophagy in lung cancer, we observed the ultrastructural changes of the A459 lung cancer cells and examined the cellular viability under different conditions." (PMID 31508368, 2019). "To investigate the effect of BCL2L1 on the apoptosis/pyroptosis of A549 lung cancer cells, we conducted cellular flow cytometry to evaluate the cell death rate in different intervention groups of A549 lung cancer cells." (PMID 31508368, 2019).
lung carcinoma (continued). "Meanwhile, we conducted rescue experiments by co-transfection of let-7a-5p inhibitors in sh-BCL2L1 transfected A549 lung cancer cells." (PMID 31508368, 2019). "To explore the biological function of BCL2L1 in the proliferation, migration, and invasion of lung cancer cells, we designed and synthesized the plasmids of shRNAs and pcDNAs to silence or overexpress the expression of BCL2L1 in A549 lung cancer cells." (PMID 31508368, 2019). "Silencing BCL2L1 attenuated the migration and invasion of A549 lung cancer cells, whereas overexpression of BCL2L1 elevated the migration and invasion of A549 lung cancer cells." (PMID 31508368, 2019). "For different subtypes of lung cancer, high expression of BCL2L1 correlates with reduced survival of LA patients (HR (95%CI) = 1.67(1.29~2.15)), but it did not affect survival time of patients with LSC (HR (95%CI) =0.79(0.62~1.02))." (PMID 30497474, 2018). "Alterations in these four target genes were then explored in 4105 lung cancer patients, and BCL2L1 and IGF1R were demonstrated to be aberrantly expressed." (PMID 30497474, 2018). "Levels of BCL2L1 were assessed in 4000 clinical samples of diverse subtypes of lung cancer biopsy samples, as well as in controls." (PMID 30497474, 2018). "Survival analysis further revealed that high expression of BCL2L1 corresponded to reduced survival of lung cancer patients (HR (95%CI) = 1.75(1.33~2.30)), while patient survival time was unaffected by expression of IGF1R (HR (95%CI) = 1.15 (0.98~1.36))." (PMID 30497474, 2018). "Results suggested that high levels of BCL2L1 decease the survival of lung cancer patients (HR (95%CI) = 1.75(1.33~2.30)), while patients survival time was unaffected by expression of IGF1R (HR (95%CI) = 1.15(0.98~1.36))." (PMID 30497474, 2018). "Either cytoplasmic or nuclear expression of BCL2L1 was found in 81.5% and 30.4% of lung cancers, respectively." (PMID 21776270, 2011). "Cytoplasmic expression of BCL2L1 and elevated BCL2L1 gene transcripts have been reported in 81.7% and 60% of lung cancers, respectively." (PMID 21776270, 2011). "Furthermore, inhibition of Eg5 demonstrated efficacy in EGFR-TKI-resistant and cisplatin-resistant lung cancer cells, and combining Eg5 and BCL2L1 inhibitors effectively killed EGFR-mutant LUAD cells refractory to EGFR TKIs." (PMID 40002279, 2025). "Similarly, let-7a-5p delivered from macrophages to lung tumor cells inhibits lung cancer cell proliferation acting, via PI3Kg signaling system, on Bcl-2-like protein-1 (BCL2L1), a potent inhibitor of apoptosis." (PMID 35406692, 2022). "As predicted by bioinformatics analysis, BCL2L1 is a putative target of let-7a-5p in lung cancer." (PMID 31508368, 2019). "Furthermore, aberrant expression of BCL2L1 significantly altered the expression of lung cancer biomarkers such as MYC, EGFR, and Vimentin." (PMID 31508368, 2019). "Moreover, let-7a-5p inhibited BCL2L1 expression and suppressed lung cancer cell proliferation, migration, and invasion." (PMID 31508368, 2019). "Therefore, it is essential to deep investigate the role of BCL2L1 for understanding the carcinogenesis and development of lung cancer." (PMID 31508368, 2019). "The expression of exosomal let-7a-5p was detected in pneumoconiosis, and all potential target genes related to exosomal let-7a-5p were predicted, among which four target genes related to lung cancer were selected for downstream analysis, including BCL2L1, IGF1R, MAPK8, and FAS." (PMID 30497474, 2018). "Studies have shown that in lung cancer, after aberrant splicing, the expression of BCL2L1, MDM2, MDM4, NUMB, and MET may play an important role in tumorigenesis, which may be due to the effects on cell apoptosis, cell proliferation, and intercellular cohesion‐related pathways." (PMID 33047900, 2020). "Therefore, BCL2L1 is an import promoter in lung cancer cell proliferation, migration, and invasion." (PMID 31508368, 2019).
lung carcinoma (continued). "Bioinformatics analysis and Kaplan-Meier survival analysis revealed that let-7a-5p could directly target BCL2L1, and aberrant expression of let-7a-5p affects the survival of lung cancer patients, which was confirmed in A549 lung cancer cells using luciferase reporter assay." (PMID 31508368, 2019). "To validate whether the expression level of BCL2L1 is causative for insensitivity to E7107 in cells, we knocked down BCL2L1 in A549 and NCIH1568 lung cancer cells using inducible shRNA targeting independent BCL2L1 sequences different from the shRNAs used in the pooled screening." (PMID 30635584, 2019). "utilized let-7a-5p as exosome cargo because high levels of this miRNA in macrophages hinder lung cancer, and the cells also treated A549 NSCLC with BCL2L1 are targets." (PMID 41357196, 2025). "Proof of concept for this approach has been shown in lung cancer models, where the Eg5 inhibitor SB743921 synergized with the BCL2L1 inhibitor WEHI-539 in two SCLC cell lines." (PMID 40002279, 2025). "We found that the expression of up‐regulated hub DEAMGs BCL2L1, CASP8, SIRT1 and CCL2 in lung cancer tissues with high metastasis was dramatically increased compared with lung cancer tissues with low metastasis." (PMID 37850256, 2024). "Expression levels of the lung cancer marker proteins MYC, EGFR, and vimentin are also altered by the aberrant expression of BCL2L1." (PMID 34193120, 2021). "In lung cancer, Let-7 targets IGF-1R to induce autophagy and blocks the function of BCL2L1/BCL2/PI3K complex to induce apoptosis and pyroptosis and inhibit cell motility." (PMID 35008539, 2021). "Comparing with cells solely transfected with sh-BCL2L1, CCK8 assays showed significant recovery of cellular viability in A549 lung cancer cells that were co-transfected with let-7a-5p inhibitors." (PMID 31508368, 2019). "One of these genes, BCL2L1, is known to collaborate with SOX2 to promote cell proliferation in lung cancer; nuclear translocation of IGF1R induced growth arrest and apoptosis resistance of lung cancer cells." (PMID 30497474, 2018). "Expression and alterations of BCL2L1, IGF1R, MAPK8, and FAS were investigated in lung cancer using TCGA database, and 4105 clinical samples provided by 13 studies were utilized in this study." (PMID 30497474, 2018). "The effect of differential expression of BCL2L1 and IGF1R on survival time of lung cancer patients was also investigated." (PMID 30497474, 2018). "Co-culturing breast or lung cancer cells with astrocytes led to upregulated survival genes, including GSTA5, BCL2L1 and TWIST1, in tumor cells." (PMID 23426399, 2013). "As a result, expression of BCL2L1 and IGF1R were found to be increased in all lung cancer subtypes." (PMID 30497474, 2018). "In accordance with previous studies, activation of IGF1R contributed to the resistance of radiotherapy in lung cancer cells; however, no data on BCL2L1 expression in LA or LSC is yet available to our knowledge." (PMID 30497474, 2018). "Interestingly, we observed tumor formation in BCL2L1 KO mouse lungs, suggesting that BCL2L1 plays a crucial role in drug resistance but has no impact on tumorigenesis in EGFR-mutated lung cancer." (PMID 39122703, 2024). "However, to the best of our knowledge, the role of let-7a-5p-BCL2L1 crosstalk in lung cancer has not been reported." (PMID 31508368, 2019). "Then, we analyzed the relationship between expression of these two genes and survival in lung cancer patient, revealing that survival was correlated with expression of BCL2L1 (HR (95%CI) = 1.75(1.33–2.30)) but not correlated with expression of IGF1R (HR (95%CI) = 1.15(0.98–1.36))." (PMID 30497474, 2018). "In a recent study oflung cancers with wild-type EGFR, the activation of EGFR upregulated SOX2, therebydecreasing apoptosis through BCL2L1, a phenomenon that was notably absent inEGFR-mutant lung cancers.A similar pathway was reported in a prostate cancer cell line, also with wild-typeEGFR." (PMID 25686219, 2015).
lung carcinoma (continued). "All of which indicated that dysregulation of BCL2L1 could not initiate or block the apoptosis or pyroptosis biological process in A549 lung cancer cells, while autophagy induced by let-7a-5p-BCL2L1 crosstalk adversely affects lung cancer cell migration and invasion." (PMID 31508368, 2019).